SOST (sclerostin)
Diseases named in the same sentence as SOST in open-access papers (continued):
Sharing a sentence is not in itself a finding about the gene and the disease.
primary hyperparathyroidism (7 papers, 2015 to 2022). "Decreased serum sclerostin levels were also shown in patients with high PTH concentration caused by primary hyperparathyroidism; on the contrary in hypoparathyroidism sclerostin levels were high." (PMID 26366174, 2015). "Therefore, the skeletal status in acromegaly differs from that in other endocrine diseases, such as primary hyperparathyroidism and Cushing’s disease, in which adequate control of the transient hormonal excess leads to (complete) bone recovery, accompanied by normalization of sclerostin levels." (PMID 34448099, 2022). "Evidence from patients with DM and primary hyperparathyroidism has revealed a negative relationship between serum iPTH and sclerostin levels." (PMID 32458213, 2020). "Intact PTH is a significant determinant of serum sclerostin levels in healthy premenopausal and postmenopausal women, patients with primary hyperparathyroidism, HD patients, and PD patients, but not in patients with non-dialyzed CKD." (PMID 31315601, 2019).
sclerosteosis 1 (7 papers, 2015 to 2025). Any sclerosteosis in which the cause of the disease is a mutation in the SOST gene. "For example, autosomal recessive inactivating mutations in SOST, which encodes the Wnt-antagonist sclerostin, result in the high bone mass disorder sclerosteosis type 1 (OMIM: 269,500)." (PMID 40462134, 2025). "Sclerosteosis type 1 is caused by ten homozygous loss-of-function mutations within the gene SOST that encodes the inhibitor of Wnt-mediated bone formation, sclerostin." (PMID 35163424, 2022).
Alzheimer disease (6 papers, 2024 to 2026). A progressive, neurodegenerative disease characterized by loss of function and death of nerve cells in several areas of the brain leading to loss of cognitive function such as memory and language. "Along with the bone-derived osteocalcin, the osteocyte-derived sclerostin may regulate the Wnt/β-catenin signaling pathway, which is essential for regulating bone metabolism and cognitive function and has been associated with Alzheimer’s disease progression." (PMID 38725641, 2024). "Furthermore, the association between elevated levels of plasma sclerostin and high brain amyloid-β deposition in older individuals at high risk of Alzheimer’s disease may be proposed as a crosstalk between bone and brain." (PMID 38725641, 2024). "Sclerostin may disrupt the Wnt/β-catenin pathway in the brain, potentially contributing to aging and the progression of Alzheimer’s disease." (PMID 40407573, 2025). "Notably, our previous cohort study along with a recent in vivo investigation, has highlighted the involvement of sclerostin, a bone-derived protein, in the pathogenesis of Alzheimer’s disease (AD), a major form of dementia." (PMID 40668308, 2025). "Otherwise, the current findings might reflect the differences between Alzheimer’s disease and PD in the pathophysiological roles of the Wnt/β-catenin pathway and sclerostin." (PMID 39104397, 2024). "Further pathophysiological and epidemiological insights will aid in understanding whether the Wnt/β-catenin pathway and sclerostin could be promising targets in human Alzheimer’s disease." (PMID 39104397, 2024).
bone metastasis (6 papers, 2014 to 2023). Transfer of a neoplasm from its primary site to bones. "Further analysis indicated that patients with high SOST expressing tumors tended to have a shorter bone metastasis-free survival; moreover, those patients were more likely to develop bone metastasis than patients with lower SOST expressing tumors." (PMID 36581888, 2022). "While the anti-sclerostin antibody romosozumab has yet to be evaluated for patients with bone metastasis, existing data from preliminary studies suggest a benefit for patients." (PMID 34503118, 2021). "Consistently, anti-sclerostin antibody also reduces the volume of bone marrow adipose tissue, suggesting that the antitumor effect of sclerostin antibody in models of bone metastasis could also be mediated, at least in part, by the bone marrow adipocytes." (PMID 32092997, 2020). "Other agents in clinical trials - in particular, neutralizing antibodies against sclerostin and DKK1 and activin A-blocking reagents - could show similar efficacy in bone metastasis-specific clinical settings." (PMID 25757219, 2014).
hip fracture (6 papers, 2020 to 2025). Traumatic or pathological injury to the hip in which the continuity of either the femoral head, femoral neck, intertrochanteric or subtrochanteric regions is broken. "Lower sclerostin levels were associated with higher bone mineral density and 85% reduction in hip fracture risk." (PMID 39537602, 2024). "For instance, longitudinal studies have reported variable associations of bone remodeling proteins derived from osteoblasts, osteoclasts, and osteocytes—including osteocalcin, c-terminal cross-linking telopeptide of type 1 collagen (CTX), and sclerostin—with prospective hip fracture risk." (PMID 41050357, 2025). "Another study showed that in patients older than 75 years who sustained a hip fracture, serum SOST and DKK1 levels were significantly higher when compared to healthy controls." (PMID 36768718, 2023). "Lower serum sclerostin and lower femoral sclerostin expression correlated with impaired trabecular microarchitecture in patients with hip fractures." (PMID 31912287, 2020). "One clinical study reported significantly increased blood levels of the Wnt/β-catenin-signaling inhibitor Sclerostin in male geriatric hip fracture patients compared to female age-matched patients, whereas the concentrations of another Wnt/β-catenin-signaling inhibitor, Dickkopf-1 were reduced." (PMID 34434120, 2021).
hyperthyroidism (6 papers, 2015 to 2023). Overactivity of the thyroid gland resulting in overproduction of thyroid hormone and increased metabolic rate. "Data regarding the association between hyperthyroidism and sclerostin are scarce, and there are only a few studies carried out in humans." (PMID 36005583, 2022). "Hyperthyroid patients also had higher sclerostin than patients with subclinical hyperthyroidism (p=0.013)." (PMID 33312059, 2020). "We determined sclerostin concentrations in sera samples from groups of patients with thyroid dysfunction (hypothyroidism, hyperthyroidism and subclinical hyperthyroidism) and compared them with each other and with those for control subjects." (PMID 33312059, 2020). "This study aimed to compare serum concentrations of sclerostin in patients with abnormal thyroid function (hypothyroidism, hyperthyroidism and subclinical hyperthyroidism) with values for healthy euthyroid individuals." (PMID 33312059, 2020). "We have previously shown a decrease of sclerostin levels during successful treatment of hyperthyroidism in a preliminary study, involving 15 patients." (PMID 26366174, 2015). "During hyperthyroidism there was a positive correlation between sclerostin and CTX (rs = 0.41, p < 0.05) and between OC and thyroid hormones (with FT3 rs = 0.42, with FT4 rs = 0.45, p < 0.05)." (PMID 26366174, 2015). "Summing up, the precise pathomechanism responsible for a decrease of sclerostin concentrations during treatment of hyperthyroidism is still unclear and requires further study." (PMID 26366174, 2015). "The aim of the study was to investigate the relationship between parathyroid hormone (PTH) and markers of bone metabolism and changes of sclerostin concentrations before and after treatment of hyperthyroidism." (PMID 26366174, 2015). "In our study sclerostin concentrations were elevated during hyperthyroidism and decreased after restoration of an euthyroid state." (PMID 26366174, 2015). "Serum sclerostin, PTH, calcium, and bone markers [osteocalcin (OC) and collagen type I cross-linked C-telopeptide I (CTX)] were measured at diagnosis of hyperthyroidism and after treatment with thiamazole." (PMID 26366174, 2015). "Successful treatment of hyperthyroidism results in a significant decrease in serum sclerostin and bone markers concentrations, accompanied by an increase of PTH." (PMID 26366174, 2015). "Analyzing other reasons for sclerostin decrease during treatment of hyperthyroidism one must also consider influence of bone markers." (PMID 26366174, 2015). "Studies have shown that the content of sclerostin in the blood circulation of patients with hyperthyroidism is significantly higher than that of patients with hypothyroidism, and the level of sclerostin is positively correlated with FT4 and negatively correlated with TSH." (PMID 36967762, 2023). "After treatment of hyperthyroidism, a significant decrease in serum sclerostin was measured." (PMID 36837860, 2023). "Thus, patients with hyperthyroidism had the highest level of sclerostin and patients with hypothyroidism the lowest." (PMID 33312059, 2020). "Here we attempted to clarify the relationship of sclerostin and thyroid hormones in humans and are the first to show differences in circulating sclerostin concentrations in patients with three different types of thyroid dysfunction (hypothyroidism, hyperthyroidism and subclinical hyperthyroidism)." (PMID 33312059, 2020). "We hypothesized that decrease in sclerostin levels in patients recovering from hyperthyroidism might be mediated by PTH." (PMID 26366174, 2015). "Another factor, potentially responsible for a decrease in sclerostin levels, might be related to an increase in physical activity during treatment of hyperthyroidism." (PMID 26366174, 2015).
hyperthyroidism (continued). "In contrast, concentrations of sclerostin were significantly higher in patients with hyperthyroidism than in control subjects (377.49±197.44 pg/mL vs 145.91±81.36 pg/mL) (Independent samples t-test, p=0.008) and patients with subclinical hyperthyroidism (Mann Whitney test, p=0.013)." (PMID 33312059, 2020). "Our results regarding the behavior of sclerostin and DKK1 serum concentrations in hyperthyroidism are consistent with earlier findings." (PMID 36005583, 2022). "Another explanation is that they complement each other, with the canonical Wnt pathway increasing sclerostin and decreasing DKK1 expression in hyperthyroidism to avoid excessive osteoblast differentiation." (PMID 36005583, 2022). "The small difference in sclerostin levels between these patients and control subjects was not statistically significant, although the mean concentration was slightly higher in patients with subclinical hyperthyroidism." (PMID 33312059, 2020).
hypophosphatemia (6 papers, 2014 to 2025). Lower than normal levels of phosphates in the circulating blood. "Treatment of HYP-mice with SPR4 peptide resulted in striking beneficial changes in serum glucose, insulin, leptin, osteocalcin, sclerostin, fat mass, 1.25(OH)2D3, and calcium with a partial correction of the hypophosphatemia." (PMID 24839967, 2014). "Likewise, circulating sclerostin levels are elevated in patients and mice affected by hypophosphatemia, and sclerostin mRNA was upregulated in the femur of the HYP mouse." (PMID 39045128, 2024). "Both, eGFR and dosage of phosphate salts in INC patients correlated with sclerostin levels in the whole study cohort, suggesting that hypophosphatemia may prevent an increase in sclerostin levels in INC patients." (PMID 35011732, 2022).
renal osteodystrophy (6 papers, 2014 to 2024). Abnormalities of bone mineral metabolism associated with chronic kidney disease. "Special emphasis is placed on internal bone mechanisms, such as hepatocyte nuclear factor 4α, transforming growth factor-β1, and sclerostin, which play crucial roles in the progression of renal osteodystrophy." (PMID 38496297, 2024). "Nevertheless, the serum sclerostin levels increase early in CKD before renal osteodystrophy is established." (PMID 32188018, 2020). "Thus, the expression of sclerostin in jck mouse, a model of progressive kidney disease occurs at early stages of CKD, even before PTH and FGF-23 increase, suggesting that sclerostin may play an early role in the development of renal osteodystrophy." (PMID 36615824, 2022). "Moreover, studies in patients with renal osteodystrophy subjected to bone biopsy have shown an inverse correlation of sclerostin and PTH levels, as well as a negative association with bone turnover." (PMID 36615824, 2022). "It is unknown if high levels of sclerostin protect against vascular calcification where Wnt/β-catenin promotes osteogenic transdifferentiation of VSMC; it is also unclear to what extent high sclerostin affects bone turnover and renal osteodystrophy." (PMID 32188018, 2020).
Cirrhosis (5 papers, 2020 to 2025). A chronic disorder of the liver in which liver tissue becomes scarred and is partially replaced by regenerative nodules and fibrotic tissue resulting in loss of liver function. "Current data on serum sclerostin levels in patients with increased fracture risk are divergent and to date only one study has examined patients with hepatic cirrhosis." (PMID 31912287, 2020). "Serum SOST levels are higher in patients with alcoholic cirrhosis than in patients with hepatitis B virus-associated cirrhosis, which may be due to age differences." (PMID 40563496, 2025). "A cross-sectional study revealed that sclerostin levels were significantly increased in patients with advanced cirrhosis when compared to those with early cirrhosis or healthy controls." (PMID 33807573, 2021). "This study assessed the quality of sclerostin to explain bone microarchitecture in hepatic cirrhosis." (PMID 31912287, 2020). "To date, the only study investigating serum sclerostin in hepatic cirrhosis reported increased levels." (PMID 31912287, 2020). "This study shows validation data of the used ELISA and evaluated sclerostin in patients with hepatic cirrhosis, compared to matched healthy controls." (PMID 31912287, 2020). "In conclusion, serum sclerostin levels reflect deterioration of bone microarchitecture and osteocyte function in patients with hepatic cirrhosis." (PMID 31912287, 2020). "In hepatic cirrhosis, sclerostin is related to altered bone microarchitecture and lower areal BMD." (PMID 31912287, 2020).
craniodiaphyseal dysplasia (5 papers, 2018 to 2025). Craniodiaphyseal dysplasia is a rare sclerotic bone disorder with a variable phenotypic expression with massive generalized hyperostosis and sclerosis, particularly of the skull and facial bones, that may lead to severe deformity. "Lastly, two different missense mutations at the same amino acid residues (the valine in position 21) have been associated with the SOST-related craniodiaphyseal dysplasia, the only dominant condition among the three related to SOST deficiency." (PMID 40943101, 2025). "Craniodiaphyseal dysplasia is a further skeletal dysplasia characterized by generalized hyperostosis and sclerosis, especially involving the skull and facial bones, due to heterogenous mutations in SOST gene (MIM# 122860)." (PMID 35096710, 2021). "Conversely, the SOST-related craniodiaphyseal dysplasia (CDD) is an autosomal dominant condition reported in just two children carrying heterozygous SOST pathogenic variants in specific amino acid residues (c.61G>A, Val21Met and c.61G>T; Val21Leu)." (PMID 40943101, 2025). "The clinical spectrum of these conditions ranges from severe craniodiaphyseal dysplasia to non-pathological high bone mass, with the severity of the condition being inversely proportional to sclerostin abundance." (PMID 33419004, 2021). "Craniodiaphyseal dysplasia (CDD, MIM 122860) is the most severe sclerostin bone dysplasia, characterized by an absence of extracellular sclerostin and a dominant negative effect." (PMID 33419004, 2021).
hypoparathyroidism (5 papers, 2015 to 2025). Hypoparathyroidism is an endocrine disorder in which the parathyroid glands in the neck do not produce enough parathyroid hormone (PTH). "In summary, to the best of our knowledge, this is the first demonstration of differences in associations of skeletal sclerostin expression with altered bone turnover in cortical and trabecular bone in ROD and post-PTX hypoparathyroidism." (PMID 36771305, 2023). "This is linked to disturbances in bone-regulating factors, including relative hypoparathyroidism and changes in hormones, like FGF-23, sclerostin, and klotho, leading to bone disease." (PMID 39941397, 2025). "We hypothesized that the relative hypoparathyroidism in patients with T2DM might result in higher sclerostin levels, but in our cohort sclerostin levels were not significantly altered in T2DM." (PMID 36190530, 2022).
mineral bone disorders (5 papers, 2017 to 2023). "Since the roles of sclerostin and DKK1 in mineral bone disorders remain inconclusive and the relationship between serum sclerostin and DKK1 with BMD in HD patients is controversial, the aim of this study was to examine the association of sclerostin and DKK1 with lumbar BMD in HD patients." (PMID 35334561, 2022). "Excess sclerostin has also been suggested to be involved in the progression of CKD and related bone mineral disorders, leading to worse patient outcomes." (PMID 36880646, 2023).
peripheral arterial disease (5 papers, 2021 to 2025). A disorder of the arteries supplying the upper and lower extremity and the visceral organs. "In a multivariable logistic analysis, in elderly subjects, sclerostin levels (OR 1.05, 95%CI 1.01–1.09, p < 0.01) were the independent predictive factor of peripheral artery disease." (PMID 33800939, 2021). "Moreover, multivariate logistic regression analysis revealed a significant independent correlation between serum sclerostin levels and peripheral arterial disease in both elderly (p = 0.008) and hypertensive subjects (p = 0.002)." (PMID 40429697, 2025). "In elderly people (>65 years old) and hypertensive patients, individuals with peripheral arterial disease (ABI < 0.9) had higher serum sclerostin levels than those without peripheral arterial disease, respectively (p < 0.001)." (PMID 40429697, 2025). "Specifically, our study revealed that T2D patients with peripheral arterial disease exhibited higher levels of sclerostin in serum compared to T2D patients without peripheral arterial disease." (PMID 37919715, 2023).
anemia (4 papers, 2020 to 2023). A reduction in the number of red blood cells, the amount of hemoglobin, and/or the volume of packed red blood cells. "Higher heart rate emerged as the most relevant clinical feature associated with 30-day mortality, alongside with anemia (median hemoglobin values 10.1 vs. 11.8; p = 0.022) and increased circulating levels of SOST (median 193 ng/mL vs. 132 ng/mL; p = 0.022)." (PMID 36943596, 2023).
aneurysm (4 papers, 2009 to 2025). Bulging or ballooning in an area of an artery secondary to arterial wall weakening. "We found increased expression of the sclerostin gene (Sost) in the aortas of mice resistant to aneurysm formation compared to both mice with aneurysms and saline controls, suggesting that sclerostin may play a role in inhibiting aortic dilatation." (PMID 19580648, 2009).
bone metabolism disorder (4 papers, 2019 to 2025). "Osteoblast hyperactivation and bone overgrowth related to sclerostin deficiency are responsible for a group of metabolic bone disorders known as SOST-related sclerosing bone dysplasia." (PMID 40943101, 2025).
Cognitive impairment (4 papers, 2023 to 2026). Abnormal cognition is characterized by deficits in thinking, reasoning, or remembering. "Plasma-EVs expressing osteocalcin, sclerostin, and nephrin were significantly higher in the cognitive impairment group compared to the normal cognition group." (PMID 38725641, 2024). "As further support for the role of SOST in neural function emerges, SOST may be a particularly accessible target for consideration of prevention and treatment of depression and cognitive impairment." (PMID 39286983, 2024).